PINK1 (PTEN induced kinase 1)
Diseases named in the same sentence as PINK1 in open-access papers (continued):
Sharing a sentence is not in itself a finding about the gene and the disease.
Parkinson disease (continued). "In this PTEN-induced kinase 1 (PINK1) mutant model organism, the treatment with ginseng, a Chinese herbal medicine, resulted in an increased lifespan, the rescue of dopaminergic neuron loss, a significant increase of dopamine in the brain, and a delayed onset of the Parkinson’s phenotype." (PMID 36674998, 2023). "Mutations in PINK1 found in PD patients may also partially affect its kinase activity, and such kinase dysfunction can contribute to the late-onset neurodegeneration in Parkinson’s disease." (PMID 34800266, 2022). "The more widespread pathology in the broader range of α-synucleinopathies, including dementia with Lewy bodies and multiple system atrophy, compared with parkinsonism caused by mutations in the genes encoding parkin and PINK1, might reflect additional cellular targets of excess actin stabilization." (PMID 33556113, 2021). "Moreover, PINK1 has been associated with the familial form of Parkinson’s disease (PD)." (PMID 33919398, 2021). "Importantly, loss‐of‐function mutations in PINK1 and Parkin are associated with rare recessive forms of Parkinson’s disease (PD) supporting an important role for mitophagy in neuronal survival and a link between its dysregulation and neurodegenerative diseases." (PMID 34152608, 2021). "In addition, mutations in PINK1 cause autosomal recessive early-onset Parkinson’s disease." (PMID 33981484, 2021). "Notably, cinnabar genetically interacts with the Parkinson’s disease associated genes Pink1 and parkin, as well as the mitochondrial fission gene Drp1, implicating KMO in mitochondrial dynamics and mitophagy, mechanisms which govern the maintenance of a healthy mitochondrial network." (PMID 33170836, 2020). "Parkin, a cytosolic E3 ubiquitin ligase protein linked with Parkinson disease (PD), mediates mitophagy in conjunction with the ubiquitin kinase Pink1 that, like Parkin, is also a mutated gene in PD." (PMID 31229895, 2019). "Loss-of-function mutations in PARK2 and PINK1, which encode the cytosolic E3 ubiquitin ligase parkin and the mitochondrial ubiquitin kinase PINK1, respectively, are the most prevalent recessive causes of Parkinson’s disease (PD), an age-dependent neurodegenerative disorder." (PMID 29809156, 2018). "Mutations in the mitochondrial protein kinase PINK1 are associated with autosomal recessive Parkinson disease (PD)." (PMID 26116755, 2015). "Taken together, the PINK1-mediated reduction of autophagic key factors during stress resulted in increased cell death, thus defining an additional pathway that could contribute to the progression of Parkinson's disease in patients with PINK1 mutations." (PMID 24751806, 2014). "Although two gene products mutated in Parkinson’s disease, PINK1, and Parkin have been found to play a central role in triggering mitophagy in mammals, how the pre-autophagosomal isolation membrane selectively and accurately engulfs damaged mitochondria remains unclear." (PMID 24569479, 2014). "Interestingly, Parkinson's disease-causing mutations decrease the processing of PINK1 by PARL." (PMID 23533695, 2013). "Interestingly, mitophagy requires genes that have been implicated in the neurodegenerative Parkinson’s disease, i.e., the serine/threonine kinase PINK1 and the E3 ubiquitin ligase Parkin, where PINK1 senses the damaged mitochondria and recruits Parkin to induce mitophagy." (PMID 23653632, 2013). "Thus, our studies suggest that abnormal DA homeostasis may precede and contribute to neuronal loss in Pink1-related Parkinsonism." (PMID 21249202, 2011). "Since disease-causing mutations in PINK1 or Parkin disrupt this pathway, patients with these mutations may not be able to clean up their damaged mitochondria, leading to the neuronal damage typical of parkinsonism." (PMID 20126261, 2010).
Parkinson disease (continued). "Our data that PINK1 deficiency becomes more evident under cell stress might explain the elevated susceptibility of dopaminergic nigrostriatal neurons in PINK1-linked Parkinsonism, since these neurons are known for high levels of oxidative stress from dopamine metabolism." (PMID 19492057, 2009). "The results expand the role of PINK1 beyond that of a damage sensor and imply a role in healthy mitochondrial function with potential relevance to Parkinson's disease." (PMID 42192124, 2026). "Conversely, chronic HFD suppresses Pink1, exacerbates oxidative stress, microglial activation and insulin resistance, accelerating Parkinson's disease pathology." (PMID 42038693, 2026). "One major mitophagy pathway eliminating damaged mitochondria is formed by the Parkinson’s disease (PD) genes PINK1 and Parkin." (PMID 41266657, 2026). "In Parkinson’s disease, it decreases α-synuclein aggregation by targeting the SNCA gene and restores mitochondrial function by correcting mutations in LRRK2 and PINK1." (PMID 40255230, 2025). "One major mitophagy pathway eliminating damaged mitochondria is formed by the Parkinson’s disease (PD) genes PINK1 and Parkin3." (PMID 40027798, 2025). "In patients with Parkinson’s disease resulting from the disruption of the PINK1/Parkin pathway, NIX functions as a neuroprotective factor by restoring mitophagy." (PMID 40655944, 2025). "PINK1 and Parkin function as part of a mitochondrial quality control pathway that is likely impaired in Parkinson’s disease." (PMID 41373767, 2025). "Familial Parkinson's disease cases, which account for approximately 5%–10% of all cases, are associated with mutations in genes such as SNCA, LRRK2, PINK1, and PRKN." (PMID 40808332, 2025). "The work emphasized the PINK1–Parkin pathway, where PINK1 accumulates on damaged mitochondria to recruit Parkin for autophagic clearance, linking these processes to neurodegenerative diseases like Parkinson’s." (PMID 41426598, 2025). "Understanding this novel regulatory mechanism provides a deeper insight into the pathological function of PINK1 in the pathogenesis of neurodegenerative diseases such as Parkinson's disease." (PMID 40064862, 2025). "Damaged mitochondria can be cleared from the cell by mitophagy, using a pathway formed by the recessive Parkinson’s disease genes PINK1 and Parkin." (PMID 40027798, 2025). "Pieces of evidence have demonstrated that the PINK1/Parkin signaling regulates mitophagy in multiple diseases, such as cardiomyopathy, Parkinson's disease, and kidney injury." (PMID 40295194, 2025). "Recent studies have also identified TRAP1 as a direct target of PTEN-induced kinase 1 (PINK1), suggesting a potential link to Parkinson’s disease (PD) pathogenesis." (PMID 40098710, 2025). "We also tested the effect of mutations in pdr-1 and pink-1, the C. elegans homologs of the human PRKN and PINK1 Parkinson’s disease genes, respectively." (PMID 41278705, 2025). "Mutations in genes such as PINK1 (PARK6) and PARKIN (PARK2) are the most common cause of a form of Parkinson’s disease that is difficult to diagnose and one of the earliest mutation-associated genes in familial autosomal recessive inheritance of PD." (PMID 40463912, 2025). "Mutations in genes, including LRRK2 (Leucine-Rich Repeat Kinase 2), PINK1, and SNCA (α-synuclein), help to explain mitochondrial malfunction and dopaminergic neural loss in Parkinson’s disease (PD)." (PMID 40430848, 2025). "The mitochondrial kinase PTEN-induced putative kinase 1 (PINK1) and the mainly cytosolic Parkin, an E3 ubiquitin ligase, have been linked to the monogenic subtype of Parkinson’s disease." (PMID 41373767, 2025). "In neurodegenerative diseases, notably, frontotemporal dementia (FTD) and Parkinson’s disease (PD), genetic mutations—including MAPT, LRRK2, PINK1, PRKN, and SNCA—have been reported to alter Nrf2 signaling, both in vitro and in vivo." (PMID 41154499, 2025).
Parkinson disease (continued). "In Parkinson’s disease (PD), RNA-seq has uncovered changes in mitochondrial-related genes (PINK1 and SNCA), autophagy pathways, and stress response networks in dopaminergic neurons." (PMID 40004464, 2025). "Both bisphenols affected pathways such as “PARK2/PINK1/UCHL1 in Young Onset Parkinson’s Disease”, “TNF activation of NF-kB Expression Targets”, and “Androgen Receptor/FKBP5 Signaling”." (PMID 41012393, 2025). "The pathogenesis of Parkinson's disease (PD) is strongly due to a disturbance in MQC related to PINK1/Parkin and lysosomal dysfunction." (PMID 39668579, 2025). "As a notable finding in this study, we investigated a fibroblast cell line from a patient with EPG5‐related parkinsonism that showed defects in PINK1/Parkin‐mediated mitophagy, reiterating our findings in cell lines from milder EPG5‐related disorders." (PMID 41053928, 2025). "Mutations in genes encoding mitochondrion-associated proteins, including PINK1, parkin, DJ-1, and CHCHD2, have been shown to cause progressive and human-like Parkinsonism, demonstrating that mitochondrial dysfunction is sufficient to induce neuronal injury." (PMID 39964974, 2025). "The absolute number of people with Parkinson’s disease who tested positive for PINK1, PARK7, VPS35 and SNCA was extremely low, precluding any detailed comments about genotype-phenotypes or participant characteristics for these groups." (PMID 39074992, 2024). "Mutations in the PINK1 and PRKN genes are the most frequent genetic cause of early-onset Parkinson disease." (PMID 39329724, 2024). "In fact, Sarm1 is involved in induced Parkinson’s-Disease-like pathology and binds to PTEN-induced putative kinase 1 (PINK1), and its activity is L-type-Ca2+-channel-dependent." (PMID 38891076, 2024). "Dysregulation of pre-mRNA processing involving key ATG genes is linked to cancer progression, whereas splice mutations in genes such as PINK1 and PRKN are associated with Alzheimer’s and Parkinson’s diseases." (PMID 39537902, 2024). "Numerous lines of evidence support the intricate interplay between Parkinson’s disease (PD) and the PINK1-dependent mitophagy process." (PMID 38711597, 2024). "HSP70 activated mitochondrial metabolism and mitophagy that protected rotenone-treated neurons and Parkinson’s disease PINK1 and LRRK2 fibroblasts from cell death." (PMID 38429623, 2024). "Parkin, PINK1, and mitochondrial fidelity play critical roles in the pathogenesis of Parkinson’s disease (PD) in humans; therefore, it would be interesting to see if a similar h-STING-Parkin-PINK-1 axis exists in human patients with PD." (PMID 38339107, 2024). "The PTEN-induced kinase 1 (PINK1)-Parkin signaling pathway helps in maintaining mitochondrial quality control and is implicated in neurodegenerative diseases like Parkinson’s disease." (PMID 38540668, 2024). "Snca and Pink1 are well‐characterized genes related to neurodegenerative diseases (e.g., Alzheimer's disease, Parkinson's disease)." (PMID 38713722, 2024). "In conclusion, FDG PET reveals abnormalities in relative regional brain glucose metabolism in Pink1−/− rats in brain regions that are important to cognition, vocalization, and limb motor control that are also impacted by Parkinson disease." (PMID 39474461, 2024). "Increased PINK1 levels were found both in the serum and CSF of patients with multiple sclerosis and in the plasma of individuals with Parkinson disease compared to healthy controls." (PMID 38695174, 2024). "Loss-of-function mutations in the genes encoding PINK1 and PRKN result in early-onset Parkinson disease (EOPD)." (PMID 38293184, 2024). "FDG PET reveals abnormalities in relative regional brain glucose metabolism in Pink1−/− rats in brain regions that are important to cognition, vocalization, and limb motor control that are also impacted by Parkinson disease." (PMID 39474461, 2024).
Parkinson disease (continued). "In contrast, fibroblasts with Parkinson’s mutations in PINK1 and LRRK2 demonstrated a significant increase in ΔΨm after 24 h of incubation (N = 5 experiments for PINK1, N = 4 experiments for LRRK2)." (PMID 38429623, 2024). "Extensive studies have been performed on mutations in the genes like SNCA, PRKN1, PRKN2, PINK1, DJ1, and LRRK2 leading to pathophysiological manifestation of Parkinson’s disease (PD)." (PMID 39766295, 2024). "Complete loss of PINK1 or PRKN function unequivocally leads to death of dopamine (DA) neurons and early-onset Parkinson disease (PD), but the impact of reduced expression or activity on disease risk later in life is debated." (PMID 38041584, 2024). "Similar post-mortem observations have been made in LRRK2 and PINK1 parkinsonism, but further comparisons would be helpful." (PMID 38614108, 2024). "PTEN-induced putative kinase 1 (PINK1/PARK6) and Parkin (PARK2), initially identified as key proteins associated with Parkinson’s disease, have been recognized for their pivotal roles in mitophagy." (PMID 39737905, 2024). "PINK1-dependent mitophagy is thought to be a factor in Parkinson’s disease and is being investigated for therapeutic targeting." (PMID 37384773, 2023). "Mutations in several genes have been associated with monogenic forms of Parkinson's disease, including SNCA, LRRK2, Parkin, PINK1, and DJ-1." (PMID 37841347, 2023). "Although PNIK1 has been shown to be involved in the pathology of age‐related diseases like Parkinson disease or Alzheimer disease, the function of PINK1 in the aging process is not fully understood." (PMID 37183600, 2023). "Although PINK1 is well-studied in Parkinson’s disease, research has also uncovered its significance in cancer cell biology." (PMID 37940999, 2023). "Adenosine 5′-monophosphate-activated protein kinase (AMPK)'s effect in PTEN-induced kinase 1 (PINK1) mutant Parkinson's disease (PD) transgenic flies and the related mechanism is seldom studied." (PMID 37868355, 2023). "PINK1/Parkin-pathway-mediated mitochondrial autophagy was first discovered in the nervous system and is one of the pathological mechanisms of Parkinson’s disease." (PMID 37808204, 2023). "TH, the rate-limiting enzyme in DA synthesis, has been shown to have decreased protein levels or decreased activity in models of Parkinson’s disease carrying mutations in LRRK2, SNCA, DJ-1 and PINK1." (PMID 36864664, 2023). "There has been an increase of attention toward the function of PINK1 in the past decade following its discovery as an autosomal recessive gene involved in the pathogenesis of Parkinson’s disease." (PMID 36823640, 2023). "Phosphoproteomics has also revealed that aberrant p25/Cdk5 signaling occurs in early-stage Parkinson’s disease in α-synuclein transgenic mice, whereas PINK1 regulates a subset of Rab GTPases." (PMID 37179123, 2023). "Parkin, an E3 ubiquitin ligase involved in Parkinson’s disease, is inactive in the basal state and is activated by PINK1 to mediate mitophagy." (PMID 36941054, 2023). "In C. elegans and Drosophila, genetic deletion of the ortholog form of human PRKN and PINK1 results in typical Parkinson-like phenotypes." (PMID 37468944, 2023). "The Parkinson’s disease genes Pink1 and Parkin mediate mitochondrial quality control mechanisms that culminate in the clearance of depolarized or dysfunctional mitochondria." (PMID 36493777, 2023). "PINK1 and parkin were originally cloned as familial Parkinson’s disease (PD) genes in human genetic analyses and have been identified as molecular guardians of mitochondria in fly genetic studies." (PMID 36979812, 2023). "PINK1/Parkin-mediated mitophagy is also altered in many other neurological disorders such as Parkinson's disease (PD) and Alzheimer's disease (AD)." (PMID 36846712, 2023). "The genetics of Parkinson’s disease has been key to unravelling the PINK1-dependent mitophagy process." (PMID 37384773, 2023).
Parkinson disease (continued). "Community-one-associated miRNA involved in regulation of autophagy-related protein PINK1 (PTEN-induced kinase 1, linked to Parkinson’s disease), MIR27A, increased with intracellular Mn." (PMID 37107179, 2023). "PINK1 and PGAM5 are known to play essential roles in maintaining mitochondrial integrity and homeostasis and have been linked to both Parkinson’s disease and defects of spermatogenesis." (PMID 37505079, 2023). "Previously, we have referred to the role of the PINK1 gene in early inherited parkinsonism, and these findings are in support of the theory that links mitochondrial dysfunction to PD." (PMID 37108382, 2023). "A major protein degradation pathway, autophagy, is critical to regulating protein turnover in neurons and has been connected to Parkinson’s disease-related mutations including SNCA, LRRK2, VPS35, parkin, Pink1 and DJ-1." (PMID 36864664, 2023). "As such, complete loss of either enzyme, PINK1 or PRKN, is invariably linked to early-onset Parkinson disease (PD)." (PMID 36469690, 2023). "In Parkinson's disease, PINK1 was found to be a primary upstream activator of Akt via regulation of PIP3." (PMID 37940999, 2023). "Familial Parkinsonism is linked to mutations in a number of genes including α-synuclein, LRRK2, parkin, DJ-1, PINK1, UCHL-1, synphilin-1, and NR4A2." (PMID 35813507, 2022). "The function of PINK1 (PTEN-induced putative kinase 1) is similar to Parkin proteins, which are both recessive inheritance genes of autosomes related to Parkinson’s disease." (PMID 36232745, 2022). "Pathogenic mutations in LRRK2 and SNCA have been associated with PD, while mutations in four genes (Parkin, DJ-1, PINK1, and ATP13A2) cause early-onset parkinsonism." (PMID 35873822, 2022). "In vitro studies have established the prevalent theory that the mitochondrial kinase PINK1 protects neurodegeneration by removing damaged mitochondria in Parkinson’s disease (PD)." (PMID 34800266, 2022). "Mn exposure also induces cellular damage through histone acetylation changes in neuronal PC2 cells, while in human neuroblastoma SH-SY5Y cells, Mn alters DNA methylation on TH, PARK2, and PINK1 genes that are vitally involved in the onset of Parkinsonism." (PMID 36142718, 2022). "Similar observations were made in a transgenic model of Parkinson’s disease where Pink1−/− rats presented reduced respiratory rate to hypercapnia (combination of hypoxia) with age." (PMID 35408858, 2022). "There has been long-term interest in drugging the PINK1-Parkin pathway with therapeutics as a treatment for Parkinson’s disease (PD)." (PMID 35754955, 2022). "We examine gene-based models, including ones linked to Early-Onset Parkinson’s Disease: PARKIN, PINK1, DJ-1, and SNCA; but we also examine LRRK2, which is linked to Late-Onset Parkinson’s Disease." (PMID 35370740, 2022). "Currently, the best studied mitophagy pathway is regulated by the Parkinson's disease (PD) proteins PTEN Induced Kinase 1 (PINK1) and Parkin (PRKN; PARK2)." (PMID 35642724, 2022). "At least two familial Parkinson’s Disease-associated genes, namely the E3-ligase PARK2 (PARKIN) and PARK6 (PINK1) were reported in the control of mitophagy." (PMID 36357363, 2022). "The PINK1/Parkin pathway, while better known for being genetic factors of Parkinson’s disease, is now known to also play a role in mitophagy." (PMID 36340034, 2022). "To do so, we used SH-SY5Y neuroblastoma cells, a neuronal model used in Parkinson’s disease and cancer studies, to characterize the pro-survival functions of PINK1 in response to the apoptosis inducer staurosporine." (PMID 35203326, 2022). "Mutations in PINK1 and PARKIN have been identified in early-onset Parkinson’s disease (PD) patients and confirmed in in vivo models." (PMID 36056001, 2022). "Autosomal recessive forms are caused by mutations in the PARK2, PINK1, and PARK genes, which approximately share a similar phenotype, characterized by early onset parkinsonism responsive to levodopa." (PMID 35893043, 2022).